CCR2 (C-C motif chemokine receptor 2)
Diseases named in the same sentence as CCR2 in open-access papers (continued):
Sharing a sentence is not in itself a finding about the gene and the disease.
encephalitis (7 papers, 2013 to 2025). An acute inflammatory process affecting the brain parenchyma. "In West Nile virus infection, CCR2 deficiency results in reduced monocyte accumulation in the brain and increased mortality from encephalitis." (PMID 23542035, 2013). "Notably, in a mouse model of USUV encephalitis, CCR2 deficient mice were protected against BBB disruption." (PMID 40918112, 2025). "Indeed, studies on anti-encephalitis caused by JEV infection showed that targeting CCR2 and other inflammatory cytokines/chemokines could all improve the occurrence of encephalitic disease progression." (PMID 34831405, 2021). "Macrophage infiltration into the CNS of TMEV-DA-infected C57BL/6 mice is dependent on the expression of CCL2 by neurons, which controls the recruitment of CCR2+ inflammatory monocytes during the most acute stage of encephalitis." (PMID 30669615, 2019). "In the context of viral encephalitis, alteration or blockade of the CCR2/CCL2 axis can significantly reduce the infiltration of inflammatory monocytes into the infected brain." (PMID 27930721, 2016). "We conclude that intracranial inoculation with infectious TMEV rapidly induces the expression of CCL2 in neurons, and this cellular source is necessary for CCR2-dependent infiltration of inflammatory monocytes into the brain during the most acute stage of encephalitis." (PMID 29202854, 2017). "Overall, we conclude that infection of the brain with TMEV rapidly induces CCL2 expression in neurons and this cellular source is central to driving CCR2-dependent infiltration of inflammatory monocytes into the brain during the most acute stage of encephalitis." (PMID 29202854, 2017). "In line with our results, it has been demonstrated that CCR2 signaling pathway is critical for monocytes mobilization in the blood and survival in a mouse model of West Nile virus (WNV) encephalitis." (PMID 27930721, 2016). "The CCR2/CCL2 axis is pivotal for leukocyte trafficking, particularly monocytes, in the context of viral encephalitis." (PMID 27930721, 2016). "While the relevance of our current findings to the neuropathological and electrophysiological sequelae of TMEV encephalitis remains to be determined, our observations lend further support to the therapeutic relevance of targeting the CCL2:CCR2 axis to confer neuroprotection." (PMID 29202854, 2017). "However, the knockout of CCR2 in C57BL/6 mice results only in a moderate decrease in seizure severity, indicating that CCR2-independent CNS inflammatory mechanisms trigger the development of seizures during viral encephalitis." (PMID 30669615, 2019). "However, the roles of CCR2 and TNF-α should be validated by using more doses and the modified treatment schedule, while this study showed that the blockade of both CCR2 and TNF-α could partially inhibit the polarization of M1 macrophages, which therefore may reduce encephalitis incidences." (PMID 34831405, 2021).
glomerulonephritis (7 papers, 2007 to 2025). A renal disorder characterized by damage in the glomeruli. "In glomerulonephritis, MCP-1 and its receptor CCR2 are implicated in activating intracellular signaling pathways that regulate podocyte and HK-2 function." (PMID 40995594, 2025). "Treatment with anti-CCL2 antibodies and CCR2 inhibitors suppresses urine protein leakage and inflammation in the tubulointerstitium and glomeruli and decreases the migration of macrophages into these tissues in a rat model of glomerulonephritis." (PMID 33159802, 2021). "CCR2+CX3CR1+ monocytes are preferentially recruited and acquire proinflammatory properties during glomerulonephritis." (PMID 38454505, 2024).
glomerulosclerosis (7 papers, 2018 to 2025). A hardening of the kidney glomerulus caused by scarring of the blood vessels. "In diabetic db/db mice, inhibiting CCR2 using a small-molecule antagonist can alleviate proteinuria, glomerulosclerosis, and kidney failure." (PMID 36969169, 2023). "CCL2 activates CCR2 on proinflammatory monocytes/macrophages and draws them into inflamed glomeruli, where myeloid cells play a vital role in podocyte injury and glomerulosclerosis." (PMID 34369383, 2021). "Several reports have shown that glomerulosclerosis and tubulointerstitial fibrosis were significantly ameliorated in CCR2-/- mice with adriamycin nephropathy, and accompanying with the reduction of macrophage and fibrocyte infiltration and inflammation in glomeruli and the tubulointerstitium." (PMID 35725391, 2022). "Importantly, CCR2 inhibition also improved glomerular injury as measured by improvements in tubular damage, glomerulosclerosis and podocyte density." (PMID 29561839, 2018). "Furthermore, the knockout of CCR2 could reduce the incidence of glomerulosclerosis and secondary tubulointerstitial damage." (PMID 36969169, 2023).
lupus nephritis (7 papers, 2016 to 2023). Glomerulonephritis in the context of systemic lupus erythematosus. "Animal experiment results show that CCR2 autoimmune-deficient mice have significantly reduced lupus nephritis." (PMID 35725391, 2022). "The MCP-1/CCR2 axis promotes the infiltration of glomerular macrophages and an increase in intracapillary cells in lupus nephritis." (PMID 37861543, 2023). "CCR2 is an inducible inflammatory chemokine receptor involved in leukocyte traffic in both humans and murine lupus nephritis." (PMID 36853827, 2023). "MCP-1/CCR2 signaling was involved in human crescentic glomerulonephrtitis and murine lupus nephritis." (PMID 27788494, 2016). "Some of the chemokines such as C-C Motif Chemokine Receptor 2 (CCR2) and CCR5 could induce glomerular macrophage infiltration and contribute to the development of glomerular endocapillary hypercellularity in lupus nephritis." (PMID 35887371, 2022).
memory impairment (7 papers, 2012 to 2024). "More recently, CCR2 deficiency was shown to prevent hippocampus-dependent spatial learning and memory impairments induced by cranial irradiation, highlighting the potential neuron-specific functions of this receptor." (PMID 24648328, 2014). "Interestingly, CCR2 deficiency has been shown to prevent hippocampal-dependent spatial learning and memory impairment observed after cranial irradiation, raising the possibility that BMD infiltrating cells might contribute to CNS dysfunction." (PMID 26842770, 2016). "In fact, studies have shown that a decrease in CCR2+ myeloid cells in APP/PS1 mice at 6 months of age was associated with increased levels of soluble oligomeric Aβ in the hippocampus and memory impairments." (PMID 31822279, 2019). "Here, we show that CCR2 signalling in CD8 TRMthat persist within the hippocampus after recovery from CNS infection with West Nile virus (WNV) significantly prevents the development of memory impairments." (PMID 39345540, 2024). "Infiltration of AD monocytes into the CNS relied on C–C motif chemokine receptor 2 (CCR2) and blockade of CCR2 in AD mice (Appswe/PS1 and Tg2576) enhanced Aβ pathology and deteriorated memory impairment." (PMID 38178136, 2024). "However, during the memory test, the CCR2 knockout TBI cohort performed at levels comparable to the sham animals, suggesting that blocking monocyte infiltration could at least partially rescue performance in the RAWM assay and prevent TBI-induced memory impairment." (PMID 29848996, 2018). "Of great interest are the data that CCR2 gene delivery in bone marrow cells rescued memory impairments of non-irradiated APPSwe/PS1 mice, suggesting a defect in the CCR2 system during AD." (PMID 23125823, 2012).
Parkinson’s (7 papers, 2018 to 2023). "Chemokines (RANTES and MCP-1) and chemokine- receptors (CCR2 and CCR5) gene polymorphisms in Alzheimer’s and Parkinson’s disease." (PMID 31447666, 2019). "In humans, a strong upregulation of CCR2 on classical monocytes in Parkinson’s patients was detected whereas the percentage of these cells was specifically downregulated, suggesting that this cellular population may have migrated to the inflamed brain." (PMID 34201693, 2021). "Thus, one can hypothesize that an accumulation of glucosylceramides or GM2 in Parkinson’s disease could participate to the production of CCL2 and to the recruitment of CCR2+ leucocytes into the brain." (PMID 33069254, 2020).
brain injury (6 papers, 2014 to 2025). Acute and chronic (see also brain INJURIES, CHRONIC) injuries to the brain, including the cerebral hemispheres, CEREBELLUM, and brain STEM. "In this study, we used three fate-mapping and two CCR2-intervention methods to assess the plasticity and pathological roles of monocytes in neonatal LPS/HI brain injury." (PMID 34976198, 2022). "For example, signaling by chemokine (C-C motif) ligand 2 (CCL2) to the chemokine (C-C motif) receptor 2 (CCR2) is a key regulator of brain infiltration by monocytes after brain trauma." (PMID 32819386, 2020). "Chemotactic protein-1 (MCP-1, CCL2) and its receptor CCR2 are involved in the inflammatory response, and proinflammatory monocytes constitute the primary monocyte subgroups following brain injury,CCR2 is expressed high on proinflammatory monocytes while CX3CR1 is expressed low or not at all." (PMID 36793730, 2023). "Thus, our findings suggest a time-window for therapeutic interference of invading Ccr2-positive, antigen-presenting cells after traumatic brain injury." (PMID 25153123, 2014). "In the current study, we investigated whether peripheral leukocytes infiltrated the brain following mild traumatic brain injury (mTBI) using a CX3CR1- and CCR2-double transgenic reporter mouse model." (PMID 41574049, 2025).
cholestasis (6 papers, 2018 to 2025). Impairment of the bile flow caused by obstruction within the liver, or outside the liver in the bile duct system. "Cenicriviroc, which is a dual antagonist of CCR5 and CCR2, has been found to be effective in slowing the progression of non-alcoholic fatty liver disease and reducing liver damage in rodents with cholestasis." (PMID 37742294, 2023). "Under cholestasis the expression of a specific chemokine subset in the liver is reduced mainly affecting the CCR2 and CXCR3 axes of immune cell trafficking." (PMID 29953538, 2018). "Cholestasis in the BDL model severely impaired pathogen-induced chemokine expression in the liver affecting CCR2- and CXCR3-dependent cell trafficking." (PMID 29953538, 2018). "A recent study suggests that targeting the CCR2/CCL2 axis can limit monocyte recruitment and reduce fibrosis and cholestasis, offering a potential treatment approach for PSC." (PMID 38273376, 2024).
chronic renal failure (6 papers, 2013 to 2024). "In our previous case-control study increased CCR2-V64I polymorphism was detected in chronic renal failure patients that requiring long-term hemodialysis when compare to the healthy controls." (PMID 25067937, 2014). "Moreover, in a rat model of chronic renal disease, it was observed that combined treatment with AT1R and CCR2 selective inhibitors was synergistically beneficial." (PMID 38732244, 2024). "Based on prior studies in the context of chronic kidney disease, we hypothesised that co-inhibition of AT1R and CCR2 may result in a decrease in β-arrestin recruitment but also highly affect CCR2–G protein signalling, possibly through allosteric modulation." (PMID 38732244, 2024). "AT1R and CCR2 were reported to functionally interact, and combined treatment with the CCR2 inhibitor DMX-200 (30 mg/kg/day) and irbesartan, another AT1R antagonist, synergistically decreased β-arrestin recruitment and inflammatory cascades in chronic kidney disease." (PMID 38732244, 2024).
cyst (6 papers, 2022 to 2026). A sac-like closed membranous structure that may be empty or contain fluid or amorphous material. "CCR2-/- mice infected with TgPHYaKOII parasites survived although, relative to WT mice infected with TgPHYaKOII parasites, they demonstrated increased weight loss and cyst numbers." (PMID 38857298, 2024). "Moreover, attenuating macrophage accumulation in Pkd1-deficient mice with Mcp1 knock-out or an antagonist of the MCP-1 receptor (also known as CCR2) reduced cyst growth and tubular injury." (PMID 36106024, 2022). "In another late-onset ADPKD mouse experiment, MCP-1 was up-regulated after Pkd1 knockout, and pharmacologic inhibition of MCP-1 receptor CCR2 (INCB3344) slowed cyst growth." (PMID 41431718, 2026). "Further, we found that Cx3cr1 regulated cortex specific accumulation of Ccr2+ KRM as loss of Cx3cr1 reduced the number of cortical Ccr2+ KRM and delayed cyst progression in a cortex-specific model of cystic kidney disease." (PMID 37256130, 2023). "Importantly, IR injury mainly affects the proximal tubule region resulting in rapid cyst expansion in the kidney cortex, thus providing us with a model to test the importance of cortex-localized, Ccr2+ KRM in a niche-specific model of disease." (PMID 37256130, 2023). "To test the hypothesis that Ccr2+ KRM promote cyst progression, we analyzed cyst severity in CM IR mice on the Cx3cr1gfp/wt and Cx3cr1gfp/gfp knockout background eight weeks post injury." (PMID 37256130, 2023). "Thus, our data indicate that Cx3cr1 controls niche specific Ccr2+ KRM accumulation and, in turn, regulates cyst progression in a model that mainly impacts the kidney cortex." (PMID 37256130, 2023).
dilated cardiomyopathy (6 papers, 2013 to 2023). Cardiomyopathy which is characterized by dilation and contractile dysfunction of the left and right ventricles. "Using a genetic dilated cardiomyopathy model where CCR2- CRM are needed for beneficial adaptation and angiogenesis, CCR2- CRM but not CCR2+ cardiac macrophages were shown to directly interact with neighbouring cardiomyocytes and thus form an integrated network within the heart wall." (PMID 36926341, 2023). "In mice with dilated cardiomyopathy, reduction of CCR2- macrophages increased mortality and hindered ventricular remodeling and coronary angiogenesis, adaptive processes required to sustain cardiac output in the face of diminished cardiac contractility, according to a recent research." (PMID 35571180, 2022). "However in conditions such as dilated cardiomyopathy (DCM), monocyte-chemotactic protein-1 (MCP-1) has been established as a homing factor of MSCs because of the presence of chemokine receptor type 2 (CCR2), a MCP-1 receptor, on the cell surface." (PMID 27259550, 2016).
endometriosis (6 papers, 2021 to 2024). The growth of functional endometrial tissue in anatomic sites outside the uterine body. "In the pelvic cavity and eutopic and ectopic endometrium of endometriosis patients, both CCR2+ monocyte-derived and tissue-resident macrophages were distinguished using scRNA-seq and traditional methods such as flow cytometry." (PMID 36369244, 2022). "MCP‐1 (CCL2) and its receptor CC motif chemokine receptor‐2 (CCR2) play a key role in endometriosis initiation and development." (PMID 36259314, 2022). "We depleted monocytes using a function-blocking CCR2 monoclonal antibody (MC21) injected into the peritoneal cavity of mice with induced endometriosis." (PMID 33536334, 2021). "Significantly elevated numbers of F4/80+, CCR2+ macrophages were recorded in mice with induced endometriosis, suggesting that increased numbers of monocyte-derived LpM are evident in mice with endometriosis." (PMID 33536334, 2021). "Furthermore, we found endometriosis to trigger continuous recruitment of monocytes and expansion of CCR2+ LpM." (PMID 33536334, 2021). "Summarizing, the implantation and growth of endometrial tissue in the peritoneal cavity may be related to the local immunity in patients suffering from endometriosis, and MDSCs with CCR2/CCR5 expression may be a key driver in endometriosis progression." (PMID 33803806, 2021). "Notably, the number of monocytes and CCR2+ LpM was significantly elevated in the peritoneal cavity of mice with induced endometriosis, above levels seen in ovariectomized controls, suggesting monocytes are continually recruited and contribute to LpM pools during lesion development." (PMID 33536334, 2021). "Moreover, in lesions recovered from Ccr2−/− and Ccl2−/− mice we could still detect monocytes using immunodetection, indicating that there is redundancy in the CCL2–CCR2 axis in the presence of endometriosis lesions and suggesting that monocytes may also be recruited via another mechanism." (PMID 33536334, 2021).
Glucose intolerance (6 papers, 2015 to 2025). Glucose intolerance (GI) can be defined as dysglycemia that comprises both prediabetes and diabetes. "Thus, CCR2-/- mice were protected from gut inflammation and glucose intolerance by oral exposure to DEP." (PMID 37400850, 2023). "Moreover, CCR2-/- mice were protected from air pollution-induced glucose intolerance and beta-cell dysfunction, suggesting a link between the level of gut inflammation instigated by DEP and glucose intolerance." (PMID 37400850, 2023). "On the contrary, mouse models lacking major components of innate immunity by either genetic (CCR2-/- mice) or pharmacological manipulation (CSF1R-inhibition) were protected from DEP-induced gut inflammation and glucose intolerance." (PMID 37400850, 2023). "In contrast, decrease of both M1- and M2-like ATMs in Epi of Ipra-treated CCR2 KO mice more strongly enhanced adipose tissue expansion without deteriorating glucose intolerance, than those of only Ipra-treated WT mice." (PMID 30382157, 2018).
Hepatitis (6 papers, 2013 to 2022). Inflammation of the liver. "Propagermanium is marketed for hepatitis in Japan and is reported to be an indirect CCR2 antagonist." (PMID 29561839, 2018). "In support of our findings, CCR2 knockout mice are resistant to hepatitis and have reduced infiltration of inflammatory monocytes." (PMID 25012628, 2014). "The monocytes emerging in the liver during hepatitis progression bare the hallmarks of inflammatory monocytes as they display a CCR2+, Gr-1+ (Ly6G), iNOS+ phenotype." (PMID 23762326, 2013). "Furthermore, we showed in the previous study that CCR2 was a critical factor for the migration of Tregs to HSCs in a T-cell mediated hepatitis mouse model." (PMID 27464894, 2016). "Previous work by others demonstrated that deficiency of CCL2, a chemokine ligand of CCR2, did not prevent hepatitis in a methionine-choline deficient (MCD) mouse model of NASH." (PMID 23762326, 2013). "Parallel to these systemic changes, liver biopsies from CPI-induced hepatitis patients show focal immune aggregates composed of cytotoxic granzyme B+CD8+ T cells co-localising with CD163+ and CCR2+ expressing MoMFs." (PMID 35454819, 2022). "With respect to ALF, CCR2−/− mice exhibit increased hepatic injury, with elevated IFN-γ and TNF-α expressions, in an acetaminophen-induced hepatitis model." (PMID 28272428, 2017). "Our findings reinforce studies in humans that have identified CCR2 and CD44 as being increased in NASH patients and they establish a possible link between these two molecules in lipid mediated hepatitis progression in so far as Ccr2−/− mice are largely protected from CD44 mediated HA binding." (PMID 23762326, 2013). "Because CCR2 and its ligands are upregulated in B6 mice and because CD44 expression is increased in LD fed B6 mice we wanted to determine if these two molecules were critical for hepatitis formation in this model." (PMID 23762326, 2013). "Therefore, we analyzed whether CCR2 and CD44 gene deleted mice were resistant to LD induced hepatitis." (PMID 23762326, 2013).